LINC00471 (long independently transcribed non-coding RNA 471)
Synonyms: C2orf52; MGC43122
Gene: Long non-coding RNA gene on chromosome 2 (231,465,513 to 231,515,851, reverse strand). Ensembl gene ENSG00000181798.
Gene Ontology:
Molecular function: pre-mRNA branch point binding
Biological process: mRNA branch site recognition
Cellular component: U2 snRNP
Diseases named in the same sentence as LINC00471 in open-access papers:
LINC00471 is named in the same sentence as 2 diseases in open-access papers, as found by Europe PMC text mining. Sharing a sentence is not in itself a finding about the gene and the disease. The quoted sentences say what the papers report.
acute myeloid leukemia (1 paper, 2022). Acute myeloid leukemia (AML) is a group of neoplasms arising from precursor cells committed to the myeloid cell-line differentiation. "LINC00471 was an essential member of the prognostic model of childhood acute myeloid leukemia and esophageal squamous cell carcinoma." (PMID 35910212, 2022).
LINC00471 also shares sentences with these, for which no sentence is quoted: esophageal squamous cell carcinoma (1 paper).